VIP (vasoactive intestinal peptide)
Diseases named in the same sentence as VIP in open-access papers (continued):
Sharing a sentence is not in itself a finding about the gene and the disease.
neuropathy (1 paper, 2016). A disorder affecting the nervous system that manifests with pain, tingling, numbness, and/or muscle weakness. "Therefore, l-glutamine is expected to exert neuroprotective effects during the development of cancer-related neuropathy and, with greater circulating antioxidant availability, enteric neurons will not need to express large amounts of VIP, thus maintaining normal neuron and varicosity size." (PMID 27635657, 2016).
ovarian carcinoma (1 paper, 2025). A malignant neoplasm originating from the surface ovarian epithelium. "Secondly, the top six genes, each with more than 100 publications (KIT, EGF, STAR, GAL, FGF2, VIP), have known established roles in ovarian cancer." (PMID 40699804, 2025).
Pleural effusion (1 paper, 2014). The presence of an excessive amount of fluid in the pleural cavity. "However, soon afterward, the patient developed rapidly progressive disease with a massive amount of left pleural effusion after the 5th cycle of VIP." (PMID 24406431, 2014).
polyp (1 paper, 2022). A usually exophytic mass attached to the underlying tissue by a broad base or a thin stalk. "A decreased mRNA expression of VIP in colorectal samples was mentioned, which is also in parallel with our results since we observed down-regulated profile of VIP in polyp samples." (PMID 35486660, 2022).
posterior uveitis (1 paper, 2007). Inflammation of the choroid as well as the retina and vitreous body. "The resulting potential modulation of the loco-regional immune microenvironment suggests that a single IVT injection of VIP-Lip is a rational therapeutic modality for posterior uveitis and other immune-mediated ocular diseases in humans." (PMID 18451986, 2007).
pterygium (1 paper, 2022). A wedge-shaped fibrovascular lesion arising from the bulbar conjunctiva and extending to the cornea. "Our findings demonstrate that VIP levels are increased in recurrent pterygium, and the levels closely correlate with SP levels." (PMID 36555331, 2022). "On the other hand, complete inhibition of the TRPV1+ stromal nerve fibers in pterygium may hinder the protective effects of neuropeptides such as VIP." (PMID 36555331, 2022). "The SP and VIP levels of pterygium tissue in the primary group who did not have a recurrence in the follow-up period (group 1) were markedly lower compared to the primary pterygia of patients who had recurrence (group 2)." (PMID 36555331, 2022). "Hence, in the present study, we aimed to examine the possible relationship between SP, VIP and TRPV1 in cases with a recurrence of pterygium." (PMID 36555331, 2022). "The possible association between TRPV1 in nerve fibers and neuropeptides such as Substance P (SP) and Vasoactive Intestinal Peptide (VIP) in the recurrence of pterygium has not been examined before." (PMID 36555331, 2022).
pulmonary edema (1 paper, 2022). Accumulation of fluid in the lung tissues causing disturbance of the gas exchange that may lead to respiratory failure. "This study aimed to investigate the protective effects of pseudoephedrine and emodin combined treatment in experimental ALI, as well as the mechanisms underlying the regulation of inflammation and pulmonary edema via the VIP/cAMP/PKA pathway." (PMID 35123524, 2022).
pulmonary sarcoidosis (1 paper, 2015). Sarcoidosis affecting the lung parenchyma. "Furthermore, broncho-alveolar lavage fluid (BALF)-derived Treg suppressive efficacy was found to increase during short-term inhaled vasoactive intestinal peptide (VIP)-treatment in pulmonary sarcoidosis, which was also associated with amelioration of clinical symptoms (i.e. dyspnea and cough)." (PMID 26376720, 2015).
pulmonary tuberculosis (1 paper, 2024). A bacterial infection that affects the lungs and is caused by Mycobacterium tuberculosis. "We present the case of a 49-year-old male patient affected by an oligo-metastatic ileal NEN, concurrently demonstrating vasointestinal peptide (VIP) and serotonin excretion, complicated by pulmonary tuberculosis." (PMID 39351119, 2024).
renal carcinoma (1 paper, 2016). A carcinoma arising from the epithelium of the renal parenchyma or the renal pelvis. "Previous data reported the same effect of VIP on β‐catenin in renal cancer cells." (PMID 26818776, 2016).
respiratory infections (1 paper, 2021). "It is not so surprising that the ACE2-equivalent ViP signature is more generalizable as a signature that is induced in respiratory infections”." (PMID 34127431, 2021).
Right ventricular hypertrophy (1 paper, 2017). In this case the right ventricle is more muscular than normal, causing a characteristic boot-shaped (coeur-en-sabot) appearance as seen on anterior- posterior chest x-rays. "In a previous study, we determined that loss of VIP gene led to increased mortality in association with progressive right ventricular hypertrophy." (PMID 28824540, 2017).
schwannoma (1 paper, 2019). A benign, usually encapsulated slow growing tumor composed of Schwann cells. "There is also some evidence to show that VIP and PACAP have a direct effect on cultured Schwann cells and schwannoma cells to promote cell survival, induce laminin synthesis as well as regulating myelin protein expression." (PMID 31920495, 2019). "It has been previously been described that VIP and PACAP treatment increases myelin protein expression in the rat RT4 schwannoma cell line, but this has not been tested in primary Schwann cells." (PMID 31920495, 2019).
sialadenitis (1 paper, 2023). Sialadenitis is an infection of the salivary glands. "Additionally, several studies have shown that VIP caused a progressive protection in the sialadenitis of NOD mice and upregulated the anti‐inflammatory factors." (PMID 37506142, 2023). "Here, we revealed that exogenous VIP upregulated the levels of IL‐2 and IL‐10, as well as alleviated sialadenitis with dry mouth." (PMID 37506142, 2023).
small intestinal disease (1 paper, 2021). "In our experiment, NSAID-induced small intestinal disease model rats intervened by berberine showed significantly change in HTR4, F2RL3, NPY, CRHR2, IL1b, VIP, AQP8, NOS1." (PMID 34284820, 2021).
synovitis (1 paper, 2019). Inflammation of a synovial membrane. "Another study also related increased VIP levels in the synovial fluid to the presence of synovitis in OA patients, suggesting that both downregulation and upregulation of VIP could contribute to the OA pathology." (PMID 31861827, 2019).
Telangiectasia (1 paper, 2022). Telangiectasias refer to small dilated blood vessels located near the surface of the skin or mucous membranes, measuring between 0.5 and 1 millimeter in diameter. "Once TRP ion channels are activated, vasoactive neuropeptides such as SP, CGRP and vasoactive intestinal peptide (VIP) are released, resulting in enhanced skin blood flow and telangiectasia." (PMID 35629392, 2022).
Thrombocytopenia (1 paper, 2022). A reduction in the number of circulating thrombocytes. "The ViP signatures reveal unique targetable cytokine pathways in MIS-C, place MIS-C farther along in the spectrum in severity compared to KD and pinpoint key clinical (reduced cardiac function) and laboratory (thrombocytopenia and eosinopenia) parameters that can be useful to monitor severity." (PMID 35577777, 2022).
Tinnitus (1 paper, 2023). Tinnitus is an auditory perception that can be described as the experience of sound, in the ear or in the head, in the absence of external acoustic stimulation. "In contrast, A1 inhibitory VIP neurons from tinnitus rats showed significant increases in nAChR-mediated excitability." (PMID 37304018, 2023). "Collectively these findings suggest that VIP neurons from animals with behavioral evidence of tinnitus show increased nAChR-evoked excitability." (PMID 37304018, 2023). "Sazetidine-A and varenicline normalized tinnitus-related losses of inhibitory input onto layer 5 PNs likely via desensitization of nAChRs located on VIP neurons." (PMID 37304018, 2023). "A significant tinnitus-related increase in nAChR-evoked excitability in response to puffed ACh was observed in VIP neurons." (PMID 37304018, 2023). "Collectively, tinnitus-related loss of nAChR signaling in A1 layer 5 PNs and increased responses to nAChR signaling in VIP neurons may, in part, underpin pathological attentional deficits in tinnitus subjects." (PMID 37304018, 2023). "Therefore, tinnitus-related increases in nAChR-mediated evoked excitability of VIP neurons has the potential to enhance the activity of layer 5 PNs." (PMID 37304018, 2023).
type 1 diabetes (1 paper, 2014). "In plantar skin of patients with type 1 diabetes for less than 3 years, there were increases in vasoactive intestinal peptide (VIP) IR nerve fibers surrounding sweat glands, indicating increased cholinergic sympathetic innervation." (PMID 24847201, 2014).
urticaria (1 paper, 2021). A vascular reaction of the skin characterized by erythema and wheal formation due to localized increase of vascular permeability. "Stress can stimulate mast cell degranulation, IgE activity, and the release of neuropeptides such as SP, CGRP, and VIP that can contribute to the pathogenesis of urticaria." (PMID 34122181, 2021).
uterine diseases (1 paper, 2020). "Neither the pro-inflammatory cytokine IL-1β nor the neuropeptide VIP is proposed as a suitable single test indicator of uterine involution disturbances or uterine diseases within the first 3 weeks of calving." (PMID 33132596, 2020).
Ventricular hypertrophy (1 paper, 2013). Enlargement of the cardiac ventricular muscle tissue with increase in the width of the wall of the ventricle and loss of elasticity. "Upregulated expression of sarcoglycan and caveolin genes in VIP KO mice supports the concept of increased force to the extracellular matrix and ventricular hypertrophy, presumably from protein products of these genes having a functional role in force transmission." (PMID 23700405, 2013).
tumor (107 papers, 1997 to 2026). "Although chronic diarrhea indicates looking for the cause in the abdomen, the tumor causing VIP secretion can also be located in other locations, such as the mediastinum." (PMID 37763032, 2023). "Elevations in VIP and the activation of its receptor are the main causes of tumor-associated and HIV-induced diarrhea." (PMID 31649543, 2019). "Tumours which secrete vasoactive intestinal peptide are associated with severe diarrhoea and electrolyte disturbances." (PMID 28965289, 2017). "VIP’s involvement in tumor growth and metastasis is linked to its regulation by immune cells." (PMID 38099290, 2023). "These tumors may secrete excessive quantities of hormone such as gastrin, insulin, vasoactive intestinal polypeptide (VIP), glucagon, or somatostatin and may be associated with distinct clinical syndromes, with approximately one third of these neoplasms becoming clinically apparent." (PMID 31263451, 2019). "VIP is a peptide that has already been described as an important tumor growth factor; its VPAC1 receptor is overexpressed in several types of cancer, such as colon, pancreas, and lung." (PMID 41162835, 2026). "Debulking surgery can significantly reduce VIP secretion by removing a large portion of the tumor mass, which helps alleviate persistent diarrhea and minimizes fluid and nutrient losses." (PMID 40647278, 2025). "While the vast majority of VIPomas are located within the pancreas, other VIP-secreting extrapancreatic neoplasms have been reported, most commonly arising from the sympathetic chain." (PMID 41195063, 2025). "Based on the suspected tumor type, laboratory tests commonly assess hormone levels such as insulin, gastrin, glucagon, vasoactive intestinal peptide (VIP), and somatostatin to identify functioning PANNETs." (PMID 40427145, 2025). "In this study, PLL (Mw = 3 kDa) was conjugated to vasoactive intestinal peptide (VIP) in a 1:1 molar ratio to enhance the delivery of 131I-ASO to VIP-receptor-positive tumour cells." (PMID 40166479, 2025). "Vasoactive Intestinal Peptide (VIP): This neuropeptide can inhibit T cell anti-tumor activity and promote the development of immunosuppressive Treg and Th2 cells." (PMID 40909268, 2025). "Complete removal of the tumor eliminates the source of vasoactive intestinal peptide (VIP), resulting in the resolution of secretory diarrhea, restoration of fluid and electrolyte balance, and, ultimately, the normalization of gastrointestinal function." (PMID 40647278, 2025). "The clinical symptoms in neuroblastoma depend on the tumor mass, the extent of metastasis and catecholamine and vasoactive intestinal peptide secretion by the tumor cells." (PMID 39049899, 2024). "Diarrhea, one of the paraneoplastic syndromes, is due to hypersecretion of vasoactive intestinal peptide by the tumor and will disappear after tumor resection." (PMID 38070095, 2024). "Functional tumours are uncommon and produce hormones and peptides including insulin, gastrin, vasoactive intestinal peptide (VIP), glucagon, somatostatin, and serotonin." (PMID 39246612, 2024). "A small subgroup presents chronic incoercible diarrhea due to the tumor’s production of vasoactive intestinal peptide (VIP)." (PMID 39328672, 2024). "VIP is capable of regulating the proliferation and differentiation of normal and tumor cells through its receptors." (PMID 39539691, 2024). "The treatment of diarrhea secondary to a VIP-producing neuroblastic tumor has two main objectives: keeping the patient stable by controlling hydroelectrolytic and metabolic disorders and tumor resection." (PMID 39328672, 2024). "Analysis of tumor-infiltrating leukocytes found that VIP antagonist increased M1/M2 ratios and macrophage phagocytosis of CT26-GFP cells." (PMID 36650220, 2023). "In immunodeficient SCID mice, VIP antagonist alone or in combination with anti-PD-1 antibody attenuated CT26 tumor growth compared with the control." (PMID 36650220, 2023).
tumor (continued). "Tumor cells produce VIP, which acts on T cells through the paracrine manner, inhibiting their anti-tumor activity and promoting the development of Treg and Th2 cells." (PMID 38099290, 2023). "As previously shown, VIP antagonist significantly attenuated tumor growth after 14 days of treatment." (PMID 36650220, 2023). "When VIP binds to VIP receptors on T cells, it sends inhibitory signals that suppress the anti-tumor activity of T cells and promote tumor cell growth." (PMID 38099290, 2023). "This argument is supported by the fact that GAL, VIP and SP are involved in neuroprotective reactions that occur in response to various pathological factors, such as inflammation, neoplasm or intoxication." (PMID 36982030, 2023). "After 14 days of treatment, we found that VIP antagonist significantly reduced tumor growth in SCID mice compared with the controls." (PMID 36650220, 2023). "VPAC2 KO cells had a slight in vivo growth delay as compared to wild-type cells and improved survival, suggesting possible indirect effects on tumor growth impacted by VIP signaling through the VPAC2 receptor in the Panc02 cell line." (PMID 36302761, 2022). "Other than neuropeptide-induced cAMP-mediated tumour progression, only the mechanism underlying VIP-induced tumour growth has been well studied and mediated via cAMP/EPAC/ERK/PI3K pathways in tumour cells." (PMID 35011543, 2022). "Treatment with VIP further reduced tumor growth with much greater inhibition in mice with HCCLM3-VIPR1 implants than in those with HCCLM3-vector implant." (PMID 35864952, 2022). "In contrast, stable expression of exogenous VIPR2 promoted VIP-induced tumor cell migration, an effect that was inhibited by the addition of a PI3-kinase (PI3K)γ inhibitor or a VIPR2-selective antagonist." (PMID 36237322, 2022). "STC1 and other genes constitute a molecular network, which endows CRC with chemoresistance.VIP can regulate the growth and function of various immune cells and tumor cells." (PMID 35252182, 2022). "Pharmacologic antagonism of VIP receptors was explored as a strategy to block autocrine signaling of VIP expressed by tumor cells that stimulates tumor growth." (PMID 36302761, 2022). "These tumours are located mostly in the pancreas and produce high levels of vasoactive intestinal peptide (VIP)." (PMID 35931878, 2022). "The VIP is a peptide with a 28 AA sequence that regulates various immune cells, promotes vasodilatation, growth and function of tumor cells." (PMID 33669938, 2021). "Only steroids had a significant sustained effect on the diarrhea of the patient with vasoactive intestinal peptide tumor." (PMID 34706762, 2021). "The receptors for VIP occurs in numerous tumor cells including thyroid, breast, lung, liver, pancreas, intestinal epithelial cells, colon, bladder, prostate, uterus, and neuroendocrine tumors." (PMID 33669938, 2021). "Tumor progression and metastatic expansion in the liver and lung with massive release of VIP, unresponsive to therapies, precipitated the WDHA syndrome and patient clinical condition until his death." (PMID 33815297, 2021). "Peptides such as secretin, gastrin, bombesin, cholecystokinin, and vasoactive intestinal peptide are believed to promote the proliferation of tumor cells." (PMID 32056066, 2020). "Vasoactive intestinal peptide (VIP) secreting tumor (VIPoma) is a rare disease, presenting with profuse diarrhea, electrolyte imbalance, and possibly fatal outcome." (PMID 32850544, 2020). "The functional tumours can cause clinical syndromes; the most commonly recognised is carcinoid syndrome, though other symptoms/syndromes can occur, for example Zollinger Ellison syndrome in gastrinoma or Werner Morrison syndrome in VIP secreting tumours." (PMID 30445941, 2018). "The clinical presentation of functioning tumours depends on the peptide hormone being secreted such as insulin, gastrin, glucagon, vasoactive intestinal peptide (VIP) and somatostatin." (PMID 31447997, 2018).